XIAP (X-linked inhibitor of apoptosis)
Diseases named in the same sentence as XIAP in open-access papers (continued):
Sharing a sentence is not in itself a finding about the gene and the disease.
colon carcinoma (continued). "This study demonstrated that XIAP acts as an E3 ubiquitin ligase for OGT, resulting in the proteasomal degradation of OGT and the inhibition of colon cancer cell growth and invasion." (PMID 32994395, 2020). "Normal O-GlcNAc-modified XIAP mediates the ubiquitin-proteasomal degradation of OGT, resulting in the inhibition of colon cancer cell growth and invasion." (PMID 32994395, 2020). "Relative RNA levels of cIAP-1, cIAP-2, XIAP, SURVIVIN, DR4 and DR5 genes were evaluated by Real Time PCR analysis in seven colon cancer cell lines." (PMID 27520705, 2016). "TLBZT elicited apoptosis in CT26 colon carcinoma, accompanied by Caspase-3, 8, and 9 activation and PARP cleavage, and downregulation of XIAP and Survivin." (PMID 23758730, 2013). "We also observed XIAP and Survivin expression in CT26 colon carcinoma after three weeks of drug treatment." (PMID 23758730, 2013). "Striking difference in TGFβ/PKA signaling activity and downstream signaling leading to XIAP downregulation was observed when highly metastatic (GEO, CBS) and their poorly metastatic colon cancer counterparts (GEORI and CBSRII) were compared." (PMID 21559296, 2011). "Immunoblot analysis of a panel of NSCLC cell lines confirmed that XIAP is widely expressed at levels comparable with the colon cancer cell lines HCT116, known to express XIAP at a level above the average reported for the NCI 60 tumour cell line panel." (PMID 19904270, 2010). "In support of this idea, we found that the XIAP protein from colon cancer tissues but not normal colonic epithelial cells exhibited the characteristic downward shift in nondenaturing gels." (PMID 32060280, 2020). "Taken together, these results show that XIAP is an E3 ubiquitin ligase of OGT, is modified by O-GlcNAc at serine 406, and this modification on XIAP leads to the polyubiquitination and degradation of OGT, resulting in the inhibition of colon cancer cell growth and invasion." (PMID 32994395, 2020). "Thus, a further research about the mutual regulatory mechanism between XIAP and OGT is needed to understand the pathogenesis of colon cancer and consider the potential therapeutic interest for colon cancer." (PMID 32994395, 2020). "In addition, the transient overexpression of XIAP WT was found to decrease of OGT levels in SW13, SW480, and SW620 colon cancer cell lines." (PMID 32994395, 2020). "Our previous report reveals that in HCT116 colon cancer cells, the BIR domains of XIAP could bind E2F1 to promote cell growth by strengthening cyclin E expression." (PMID 31811115, 2019). "Given their function in regulating cell cycle and survival, effects on cyclin D1 and XIAP may contribute to IRS-1 mediated enhancement of cell proliferation and inhibition of apoptosis in colon cancer cells." (PMID 28414818, 2017). "Our most recent studies show that RING domain of XIAP is crucial for XIAP upregulation of Cyclin D1 expression, while BIR domains specifically mediate E2F1 transactivation and Cyclin E expression in human colon cancer HCT116 cells." (PMID 27447744, 2016). "Unexpectedly, we did not detect an obvious reduction of XIAP expression in the colon cancer cells treated by two compounds in combination." (PMID 24874286, 2014). "XIAP and Survivin were overexpressed in CT26 colon carcinoma." (PMID 23758730, 2013). "Therefore, it could explain that stable XIAP overexpression would have a smaller effect on OGT and total O-GlcNAc levels in MDA-MB231 and A549 cells than in HCT116 colon cancer cells." (PMID 32994395, 2020). "Indeed, the most potent way to reduce the efficiency of apoptosis experimentally in HeLa cells (i.e. increase tswitch or reduce fPARP) and generate “half-dead” cells, appears to be to interfere with the levels or activity of XIAP; the same is true in HCT116 human colon carcinoma cells." (PMID 22570596, 2012).
leukemia (53 papers, 2004 to 2025). A malignant (clonal) hematologic disorder, involving hematopoietic stem cells and characterized by the presence of primitive or atypical myeloid or lymphoid cells in the bone marrow and the blood. "In another study, X-linked inhibitor of apoptosis protein (XIAP) was highly expressed in various leukemia cells, and the inhibition of XIAP restored TRAIL sensitivity in resistant cells and primary blasts." (PMID 38909249, 2024). "Berberine induced apoptosis in leukemia cells by inhibiting the expression of X-linked inhibitor of apoptosis protein (XIAP)." (PMID 35422844, 2022). "Overexpression of XIAP has been shown to be associated with activated AKT in many cancers including leukemia." (PMID 28704451, 2017). "Embelin treatment of the leukemia cell line HL 60 caused a reduction in XIAP protein levels and increased caspase 3 and caspase 9 cleavage." (PMID 24603802, 2014). "As the phosphorylation of proapoptotic proteins, Bim and Bax cause a decrease in proapoptotic potential, antiapoptotic factors Mcl-1 (induced myeloid leukemia cell differentiation protein) and XIAP (x-linked inhibitor of apoptosis protein) reduce both protein stability and anti-apoptotic properties." (PMID 36555740, 2022). "XIAP, a well-known inhibitor of apoptosis, was found to be overexpressed in various cancer types, including leukemia, allowing cancer cells to escape the apoptotic process." (PMID 37624039, 2023). "Survival time of mice injected with a 1:1 mixture of control and strong XIAP KD cells nearly doubled when compared with mice injected with a moderate XIAP KD population in their mixture; time to full‐blown leukemia increased from 25 to 46 days." (PMID 36416169, 2023). "The antisense oligonucleotide AEG35156 specifically targets XIAP and was clinically tested in more than 100 patients, leukemia and lymphoma patients among them." (PMID 36416169, 2023). "For example, overexpression of BCL-2, an X-linked inhibitor of apoptosis protein (XIAP), and myeloid cell leukemia 1 (MCL-1) blocks the intrinsic apoptotic pathway and confers resistance to chemotherapy in leukemia." (PMID 35992795, 2022). "Roles of survivin and XIAP in celecoxib-mediated effects were also seen in leukemia and myeloma cells." (PMID 33807213, 2021). "Treatment with XIAP inhibitors brought significant reduction in malignant proliferation in a series of cancers, including gastric cancer, leukemia, and others." (PMID 33138314, 2020). "Down regulation of PI3K/AKT signaling using the IAP inhibitor, GDC-0152, which targets BIRC2, BIRC3, and XIAP has been shown to result in the induction of apoptosis in human leukemia cells." (PMID 27074575, 2017). "OA treatment was able to effectively reduce BIRC5 expression in lung cancer, ovarian cell carcinoma, and leukaemia as well as XIAP expression in hepatocellular carcinoma." (PMID 28791312, 2017). "An in vitro study using leukemia cells observed that Embelin reduced XIAP protein expression as detected by western blot." (PMID 26347311, 2015).
leukemia (continued). "Apoptosis induced by xanthohumol, which is correlated with the downregulation of XIAP, was also reported in leukemia cells in vitro." (PMID 25949267, 2015). "It is worthy of note that normal B-cells show significantly lower levels of transcription of MCL1 and XIAP compared to CLL cells perhaps providing a rationale for the preferential toxicity of CDKI-73 in leukemia cells." (PMID 24495868, 2014). "CuE at 1–10 μM has also consistently decreased levels of the anti-apoptotic proteins XIAP, Survivin, and Mcl-1, and increased levels of the pro-apoptotic protein Bax in human leukemia HL-60 cells." (PMID 25072848, 2014). "This notion is supported by former publications revealing that STS decreases the level of XIAP in leukemia cells and in MCF-7 cells." (PMID 22860037, 2012). "Additionally, circ-PAN3 acts as a critical mediator of chemoresistance in leukemia cells through targeting miR-153-5p and miR-183-5p-XIAP regulatory axis." (PMID 39866238, 2025). "To investigate whether XIAP inhibition delayed leukaemia progression in vivo, we established a xenograft model in NOD/SCID mice by subcutaneous injection of HEL cells." (PMID 37154878, 2023). "Altogether these findings raise the possibility that embelin alone or in combination with inhibitors of PI3-kinase/AKT pathway may have therapeutic usage in leukemia and possibly other malignancies with up-regulated XIAP pathway." (PMID 28704451, 2017). "Further, embelin treatments decreased XIAP protein levels in leukemia cells." (PMID 24603802, 2014). "Thus, As2 yields similar results in sensitizing leukemia cells to chemotherapy, as, for instance, small-molecule XIAP inhibitors that showed results against acute leukemia cells with Bcl-2-mediated resistance, synergizing with TRAIL (TNF-related apoptosis-inducing ligand) or Fas activation." (PMID 38731935, 2024). "In addition, studies also found that a low dose (300 nM) of MG-132 combined with flavopiridol could induce apoptosis of leukemia cells by reducing the amounts of XIAP and Mcl-1 and the activity of NF-κB63." (PMID 37537243, 2023). "It has been found that embelin, the XIAP inhibitor, induces TRAIL-mediated apoptosis by upregulating DR4 and DR5 expression in human leukemia cells." (PMID 34282169, 2021). "In this study, we found that inhibition of XIAP augments the effects of BBR on leukemia phenotypes by suppressing the serum levels of ALT, AST and WBC in xenograft mice, indicating BBR alleviated ALL condition by suppressing XIAP." (PMID 32062612, 2020). "In several leukemia cell lines (THP-1, HL-60, U937, and K562) piceatannol induced apoptosis, downregulating X-linked inhibitor of apoptosis protein (XIAP) expression, regardless of the inhibition of ROS generation." (PMID 30893846, 2019). "XIAP inhibitors already approved for clinical use, such as DQA, may be of great interest to explore their anti-leukemia effect and their potential therapeutic use in combination with conventional chemotherapy." (PMID 24952669, 2014).
lung carcinoma (48 papers, 2010 to 2025). "The whole skin extract of Venenum bufonis has also been shown to cause lung cancer cell death by downregulating XIAP." (PMID 38044583, 2024). "A limitation to this approach, however, is that upregulation of XIAP is associated with cisplatin resistance in head and neck cancer and increased Akt expression and activity are associated with acquired cisplatin resistance in lung cancer cells." (PMID 32832155, 2020). "In gastric and lung cancer cell lines, the miRNA cluster miR-200bc/429 was shown to promote apoptosis by targeting B-cell lymphoma 2 (Bcl-2) and X-linked inhibitor of apoptosis protein (XIAP), which sensitized those resistant cell lines to vincristine as well as DDP15." (PMID 25514838, 2014). "For example, miR-7 regulates apoptosis and malignant behavior of HeLa and C33A cells by targeting XIAP in lung cancer." (PMID 38271114, 2024). "Overall, the results suggest that TRAF2-NFκB activation in KEAP1 R320Q and R470C overexpressing A549 cells protects lung cancer cells against apoptosis and that XIAP and BIRC family of proteins regulate the process." (PMID 38184997, 2024). "The antitumor efficacy of the drug in combination with XIAP siRNA was investigated in Balb/C mice with lung cancer." (PMID 36430771, 2022). "Inhibition of XIAP or Survivin enhances postradiotherapy cell survival in lung cancer cells H460 compared to controls." (PMID 35992856, 2022). "For example, in non‐small cell lung cancer models, XIAP antagonist HM90822B was effective as a monotherapy, particularly in cases with activated EGFR signaling." (PMID 35224804, 2022). "We also showed that ANTP-SMACN7 promoted cell apoptosis through the inhibition of XIAP and activation of caspase-3 and caspase-9 in lung cancer cells after irradiation with high-LET IR." (PMID 34546667, 2021). "We explored the effects of Ym155, a reported survivin inhibitor, on the expression of survivin and XIAP in lung cancer cells." (PMID 34563224, 2021). "The results showed that ANTP-SMACN7 significantly promoted cell apoptosis through the inhibition of XIAP and the activation of caspase-3 and caspase-9 in lung cancer cells after irradiation with high-LET IR." (PMID 34546667, 2021). "Lung cancer cell line NCI-H522 treated with AT-101 showed a significant decrease in XIAP, cIAP-1, and cIAP-2 protein expressions compared with the control group." (PMID 34712428, 2021). "In lung cancer, micro RNAs seem to be a dominant initiator of XIAP, regulating cell proliferation and apoptosis." (PMID 33138314, 2020). "Several micro RNAs, such as miR-142 and miR-CHA1, were reported to participate in XIAP-mediated cell proliferation and apoptosis in human lung cancer." (PMID 33138314, 2020). "We provide evidence supporting that an inhibitor targeting the BMP and TGFβ type I and type II receptors will result in the greatest downregulation of Id1, TAK1, and XIAP and induction of apoptotic cell death of lung cancer cells." (PMID 27048361, 2016). "PIK3CA, XIAP and Rab5a have previously been reported in lung cancer and we have reported the effect of the rest of the mentioned genes for the first time." (PMID 23874428, 2013). "The undertaking of this study was encouraged by reports that XIAP downregulation in lung cancer using ASOs can be synergistic with other therapeutic modalities used in the treatment of the disease." (PMID 19904270, 2010). "As a result, the combination of GA and XIAP inhibition is a promising lung therapy for lung cancer." (PMID 36430771, 2022).
lung carcinoma (continued). "And XIAP-mediated protection of H460 lung cancer cells against cisplatin." (PMID 35992856, 2022). "Initially, we analyzed whether expression levels of the investigated IAP family members survivin, livin, XIAP, and BRUCE were associated with survival in patients with lung cancer." (PMID 34439255, 2021). "To investigate whether other IAP family members could serve as prognosticators in lung cancer patients, we next estimated the pooled HRs of studies providing XIAP or livin expression data for survival analysis." (PMID 34439255, 2021). "HTRA3 promotes drug-induced apoptosis through XIAP cleavage in lung cancer cells." (PMID 33425760, 2020). "Additional work from our lab showed that in colorectal and lung cancer cells downregulation of XIAP following ONC201 treatment correlated with whether the effects of the compound were apoptotic or anti-proliferative." (PMID 33144917, 2020). "ING5 overexpression up-regulated the expression of pro-apoptotic proteins AIF and cytochrome c, and down-regulated the expression of anti-apoptotic proteins Bcl-2, XIAP and survivin, accounting for its apoptosis-induced role in lung cancer cells by mitochondrial pathway." (PMID 27409347, 2016). "We found that XIAP was also an upstream regulator of TAK1 in lung cancer cells." (PMID 27048361, 2016). "BMPRII regulates the expression of XIAP in lung cancer cells, which activates TAK1." (PMID 27048361, 2016). "Since DMH2 inhibits BMPRII, we examined whether the downregulation of BMPRII effects the expression of XIAP in lung cancer cells." (PMID 27048361, 2016). "Moreover, increased radiosensitivity was reported in chondrosarcoma cells, laryngeal carcinoma, colorectal carcinoma or lung carcinoma upon genetic silencing of XIAP." (PMID 25927408, 2015). "High levels of XIAP in lung cancer cells resulted in cisplatin mediated apoptosis resistance, and this apoptosis could be restored once XIAP was silenced." (PMID 26071313, 2015). "Besides small-molecule inhibitors of IAP proteins, antisense oligonucleotides targeting XIAP were recorded to increase radiosensitivity in preclinical models of lung cancer." (PMID 25927408, 2015). "Therefore, XIAP may contribute to the insensitivity of SHP2 inhibitors to suppress lung cancer cell proliferation and induce apoptosis." (PMID 39992860, 2025). "In addition, the XIAP/TAK1/NF-κB pathway is being studied in lung cancer as well." (PMID 33138314, 2020). "The BMP receptor inhibitors JL5 and DMH2 have been shown to cause a greater decrease in the expression of the BMP signaling proteins ID1, XIAP, and TAK1, and induce more cell death of lung cancer cell lines than the BMP inhibitors DMH1 and LDN." (PMID 31744505, 2019). "We demonstrate that a small molecule inhibitor of BMP receptors downregulates the expression of XIAP and TAK1 in lung cancer cells." (PMID 27048361, 2016). "The enhanced expression of miR-200bc/429 cluster resulting decrease of BCL-2 and XIAP protein, which make the gastric SGC7901/VCR and lung cancer A549/CDDP became sensitive to VCR/CDDP induced apoptosis." (PMID 25342041, 2014). "XIAP (BIRC4), Survivin (BIRC5), Livin (BIRC7), and BRUCE or Apollone ((BIRC6) are four members of the IAP family that play an important role in the development of chemoresistant lung cancer." (PMID 36800962, 2023).
lung carcinoma (continued). "Moreover, TAFs-exosomes promote RNA stability and XIAP transcription by transporting the lncRNA SNHG12 to bind to HuR, thereby enhancing DDP resistance in lung cancer." (PMID 35587143, 2022). "The present study revealed that the SMAC mimetic compound AT101 treatment down-regulated XIAP, cIAP1, and cIAP2 mRNA and protein expressions while increasing caspase-6 and caspase-7 mRNA and protein expression levels in NCI-H522 lung cancer cell line to favor total apoptosis in these cells." (PMID 34712428, 2021). "Knockdown studies demonstrate that both XIAP and TAK1 regulate the survival of lung cancer cells." (PMID 27048361, 2016). "It was reported that miR-200bc/429 cluster could play a role in the development of MDR in both gastric and lung cancer cell lines via targeting BCL2 and XIAP." (PMID 23372675, 2013).